RLF (RLF zinc finger)
Description:
May be involved in transcriptional regulation.
Synonyms: ZNF292L; Zn-15L
Tractability: PROTAC: UniProt records ubiquitination sites on it; ubiquitination databases record sites on it.
Gene: Protein-coding gene on chromosome 1 (40,161,387 to 40,240,921, forward strand). Ensembl gene ENSG00000117000.
Subcellular location: Nucleus
Subcellular location (Human Protein Atlas): Nucleoplasm; Nucleoli
Gene Ontology:
Molecular function: protein binding; DNA binding; DNA-binding transcription activator activity, RNA polymerase II-specific; DNA-binding transcription factor activity, RNA polymerase II-specific
Biological process: positive regulation of DNA-templated transcription; positive regulation of transcription by RNA polymerase II; regulation of transcription by RNA polymerase II
Cellular component: nucleus
Genetic constraint (gnomAD): Loss-of-function variants: 7 observed, 150.75 expected, observed/expected ratio (o/e) 0.0464, 90% interval 0.025 to 0.087. The upper end of that interval is the gene's LOEUF score, 0.087, which puts it in group 1 of 6, group 1 being the genes least tolerant of losing a copy. Missense variants: 1,571 observed, 2,240.8 expected, observed/expected ratio (o/e) 0.7, 90% interval 0.67 to 0.73. Synonymous variants: 749 observed, 785.34 expected, observed/expected ratio (o/e) 0.95, 90% interval 0.9 to 1.01.
Homologues: Orthologues: chimpanzee RLF (99% identical), macaque RLF (99% identical), pig RLF (95% identical), rabbit RLF (94% identical), dog RLF (94% identical), guinea pig RLF (93% identical), rat Rlf (89% identical), mouse Rlf (83% identical), tropical clawed frog rlf (44% identical), zebrafish rlf (35% identical). Paralogues in human: ZNF292 (31% identical), ZNF654 (14% identical).
Diseases named in the same sentence as RLF in open-access papers:
RLF is named in the same sentence as 8 diseases in open-access papers, as found by Europe PMC text mining. Sharing a sentence is not in itself a finding about the gene and the disease. The quoted sentences say what the papers report.
pancreatic cancer (2 papers, 2014 to 2019). "The upstream sequence of exon 5 of RLF gene (ENST00000372771) was acquired in pancreatic cancer cell line PA043, and was found to be a sequence from exon 2 to part of exon 5 of ZMPSTE24 gene (ENST00000372759)." (PMID 24533689, 2014). "Among them, ELF4 has been found to be expressed during pancreatic development and RLF overexpression has been correlated to poor survival in pancreatic cancer patients strengthening the possibility of their involvement in the pathogenesis of PDAC, which could be explored further." (PMID 31795960, 2019).
immunotoxicity (1 paper, 2024). "According to the report, certain safety factors need to be evaluated: determination of any potential immunotoxicity from rLf ingestion, potential effects of rLf in iron homeostasis, any trace of alloimmunization, and the pathway that rLf potentially goes through during the digestion." (PMID 39728554, 2024).
mammary tumor (1 paper, 2017). "Therefore, the effect of LeTx and its components (rLF, rPA) on proliferation of primary mammary tumor cells was evaluated in vitro." (PMID 28415766, 2017).
infection (2 papers, 2023 to 2024). The state of being infected such as from the introduction of a foreign agent such as serum, vaccine, antigenic substance or organism. "Consistent with the viral loads in the lungs, hamsters that were administered with rDS plus rLF or rDS-F plus rLF showed no or few lung pathological changes, which were similar to those of no infection, after the Delta or Wuhan SARS-CoV-2 challenge." (PMID 38299865, 2024).
tumor (2 papers, 2017 to 2019). "Interestingly, we have identified several transcription factors like TRPS1, NFAT5, FoxF2, ELF4, RLF etc. which haven’t previously been reported to be involved in PDAC but shown to induce EMT, angiogenesis or proliferation of tumours in other organs." (PMID 31795960, 2019).
RLF also shares sentences with these, for which no sentence is quoted: infarction (1 paper); oral cancer (1); ovarian carcinoma (1).